ABCB1 (ATP binding cassette subfamily B member 1)
Diseases named in the same sentence as ABCB1 in open-access papers (continued):
Sharing a sentence is not in itself a finding about the gene and the disease.
heroin addiction (3 papers, 2018 to 2020). "For example, genetic polymorphisms of ABCB1 affected the dosage of methadone in the treatment of opioid or heroin addiction." (PMID 33329709, 2020). "This study used the completion/incompletion of MMT as the compliance index and the negative rate of urine morphine test as the curative effect index, recruited heroin addicts from Shanghai as research objects, and studied the impact of the ABCB1/OPRM1 gene SNPs on the MMT curative effect." (PMID 30420869, 2018).
Hyperbilirubinemia (3 papers, 2016 to 2022). An increased amount of bilirubin in the blood. "The metabolism of ATV is also partially governed by the P-gp encoded by the ABCB1, and patients carrying C3435T ABCB1 SNP may be at risk of hyperbilirubinemia and severe jaundice as well." (PMID 35250581, 2022).
Hypercholesterolemia (3 papers, 2016 to 2018). An increased concentration of cholesterol in the blood. "However, we concluded that in a low dose of atorvastatin, ABCB1 and ABCC1 polymorphisms may have an effective impact on atorvastatin efficacy in reduction of LDL-C serum level in Iranian patients with primary hypercholesterolemia." (PMID 27238935, 2017).
liver toxicity (3 papers, 2018 to 2024). "In the multivariate model, HCV coinfection was independently associated with higher risk of developing liver toxicity (aOR = 8.00, 95%CI 1.27–50.29; p = 0.027), whereas ABCB1 rs1045642 CT/TT genotypes (aOR = 0.10, 95%CI 0.02–0.47; p = 0.004) was associated with a lower risk." (PMID 30419834, 2018). "For ABCB1 rs1128503, 86.4% of patients with the GG genotype developed grade 3–4 hepatotoxicity, compared to 44.4% of patients with GA or AA genotypes (p = 0.002 in a dominant model)." (PMID 39771563, 2024). "It is worth mentioning that there is little information in the literature regarding studying the association of ABCB1 SNPs and the development of ASM-induced liver toxicity among epileptic patients." (PMID 37760947, 2023).
metastatic carcinoma (3 papers, 2018 to 2025). A carcinoma which has spread from the original site of growth to another anatomic site. "As we found DLK1 to be expressed in a subset of metastatic cancers apart from ACC, we hypothesized that ADCT-701 would be highly effective against DLK1+ tumors with low or no ABCB1 expression such as SCLC." (PMID 39416174, 2024).
prostate tumors (3 papers, 2017 to 2024). "In our study, low ABCB1 expression in prostate tumors hints at reduced chemotherapeutic resistance via the ABCB1 pathway." (PMID 38534761, 2024). "As prostate tumors often develop taxane resistance, in this study we sought to ascertain the impact of FABP5 upon docetaxel resistance in a taxane-resistant PC cell-line harboring ABCB1 overexpression." (PMID 37796964, 2023). "However, the expression of the protein ABCB1, not its RNA levels, was shown to correlate with the Gleason score in prostate tumors, possibly explained by a lower efficiency of RNA evaluation in those samples." (PMID 28938627, 2017).
substance abuse (3 papers, 2013 to 2020). The use of a drug for a reason other than which it was intended or in a manner or in quantities other than directed. "Among the articles reviewing the association between the CYP2B6*6 haplotype or the ABCB1 (rs1045642) SNP and continued illicit substance abuse among MMT patients, only two articles provided data on each gene of interest." (PMID 24489693, 2014). "Indeed, the effects of ABCB1 polymorphisms on substance abuse has been reported previously." (PMID 33329709, 2020). "These endogenous or some exogenous ABCB1 substrates may contribute in the formation of substance abuse in the central nervous system." (PMID 33329709, 2020). "Significant differences between addicts and controls in relation to schooling, marital status, social security family history of substance abuse (p <0.001), Int8-VNTR SLC6A3 gene (p= 0.015) and SNP 3435C>T ABCB1 gene (p= 0.001) were found." (PMID 24892317, 2013).
viral infection (3 papers, 2018 to 2024). "The regulation of ABCB1 gene expression is complex and may involve various factors such as viral infection, inflammation, and antiretroviral therapy." (PMID 37512019, 2023).
acute renal failure (2 papers, 2016 to 2022). "Although in the present case moderate acute renal failure probably played a role, more clinical data are required to elucidate the impact of ABCB1 polymorphism on rivaroxaban pharmacokinetics and bleeding complications." (PMID 28066243, 2016).
adenoma (2 papers, 2013 to 2015). A neoplasm arising from the epithelium. "The ABCB1 C-rs3789243-T and NFKB1 -94ins/del homozygous variant genotypes were associated with low ABCB1 mRNA levels in morphologically normal sigmoid tissue from adenoma cases (P<0.05 for both)." (PMID 23977225, 2013). "In individuals with adenomas, we found that carriers homozygous for the ABCB1 C-rs3789243-T and NFKB-94 deletion variant alleles have significantly lower ABCB1 mRNA levels in morphologically normal tissue suggesting that these polymorphisms cause lower ABCB1 mRNA levels." (PMID 23977225, 2013). "Furthermore, our results suggests that the observed low ABCB1 mRNA level in adenoma tissue must be caused by changes is the concentration of transcription factors other than NF-κB p50 as NFKB1 mRNA levels was unchanged in adenoma tissue." (PMID 23977225, 2013). "In conclusion, this study found that ABCC2 and ABCG2 gene expression levels were altered in mild/moderate dysplasia in the normal-adenoma-carcinoma sequence suggesting that these ABC transporters are involved in early carcinogenesis similar to ABCB1." (PMID 25793771, 2015). "ABCB1 C-rs3789243-T and NFKB1 -94ins/del homozygous variant genotypes were associated with lowered ABCB1 mRNA levels in morphologically normal tissue from adenoma cases." (PMID 23977225, 2013). "ABCB1 mRNA levels were also lower in adenomas and carcinomas compared to morphologically normal tissue from the same individuals." (PMID 23977225, 2013). "We have previously reported low mRNA levels of ABCB1 in adenomas and carcinomas and this may suggest similarities in the regulation of gene expression of these two ABC transporters in colorectal carcinogenesis." (PMID 25793771, 2015). "In order to elucidate whether ABCB1 mRNA levels are diminished as an early event in colorectal carcinogenesis, individuals with adenomas were further subdivided into mild/moderate dysplasia (N = 89) and severe dysplasia (N = 12)." (PMID 23977225, 2013). "Furthermore, ABCB1 mRNA levels were lower in adenomas and carcinomas compared to morphologically normal tissue from the same individuals (P<0.01)." (PMID 23977225, 2013). "Therefore, assuming that a lowered level of ABCB1 mRNA results in low ABCB1 activity in the adenomas, this would lead to a higher intracellular exposure to various carcinogenic substrates of the ABCB1 transporter." (PMID 23977225, 2013). "In contrast, ABCB1 mRNA levels in the carcinogenic tissue and the morphologically normal tissue surrounding the tumour are lowered independently of the studied polymorphisms in ABCB1 and NFKB1 suggesting any regulation by these polymorphisms is lost once adenomas have been formed." (PMID 23977225, 2013). "In the present study our aim was to assess the intestinal levels of ABCB1 and NFKB1 mRNA in adenoma and CRC cases and in control subjects in order to characterize the role of ABCB1 in the development of CRC." (PMID 23977225, 2013).
Arrhythmia (2 papers, 2021 to 2023). Any cardiac rhythm other than the normal sinus rhythm. "The confirmation of the ABCB1 3435C > T polymorphism influence on the course of fetal arrhythmia requires a multicenter, prospective, randomized, and controlled trial." (PMID 36768172, 2023). "Specific inhibitors of other dox transporters (ABCB1, ABCC1) are known to cause cardiotoxicity manifested as QT prolongation and arrhythmias." (PMID 34944997, 2021).
Burkitt lymphoma (2 papers, 2020 to 2023). A rare form of malignant mature B-cell non-Hodgkin lymphoma. "Similarly, the coexpression of survivin and P-gp/ABCB1 was determined to be responsible for resistance to the conventional treatment of Burkitt lymphoma (BL), showing that treatment with verapamil, a P-gp/ABCB1 inhibitor, or Survivin siRNA suppressed the proliferation of all drug-resistant BL cells." (PMID 37627134, 2023).
cervical adenocarcinoma (2 papers, 2019 to 2023). An adenocarcinoma arising from the cervical epithelium. "The IC50 values of paclitaxel, vincristine, and docetaxel against KBvin and ABCB1/Flp-InTM-293 cells were significantly higher than those against human cervical adenocarcinoma (HeLa S3) and Flp-InTM-293 cells, respectively." (PMID 37259354, 2023).
chorioamnionitis (2 papers, 2018). A morphologic finding indicating inflammation of the fetal sac membranes. "Up-regulation of ABCB9, ABCC2 and ABCF2 mRNA was detected in chorioamnionitis (p<0.05), whereas placental ABCB1 (P-gp; p=0.051) and ABCG2 (breast cancer resistance protein-BCRP) mRNA levels (p=0.055) approached near significant up-regulation." (PMID 29402780, 2018). "It is possible that while chorioamnionitis increases ABCB1 mRNA levels a simultaneous increase in miR-331-5p blocks P-gp protein production." (PMID 29402780, 2018). "We have previously demonstrated that chorioamnionitis induces ABCB1 mRNA expression but decreases P‐gp protein levels." (PMID 29691980, 2018). "This latter result is consistent with a previous study demonstrating that chorioamnionitis increased ABCB1 mRNA in the human placenta." (PMID 29402780, 2018). "Similarly, there was a significant correlation between the severity of chorioamnionitis and the increased expression of ABCB1, ABCC2, ABCF2 and ABCG2." (PMID 29402780, 2018).
clear cell renal carcinoma (2 papers, 2016 to 2022). A malignant epithelial neoplasm of the kidney characterized by the presence of lipid-containing clear cells within a vascular network. "For instance, high intrinsic ABCB1 expression in clear cell renal carcinoma might render nintedanib treatment ineffective." (PMID 27367030, 2016). "With respect to RCC-FG2, this clear cell renal cell carcinoma line showed an effect of ITZ, even though it does not express ABCB1, indicating that an additional effect of ITZ may be at play." (PMID 35721223, 2022).
co infection (2 papers, 2013 to 2023). "In conclusion, this study highlights the significant increase in CYP2B6 gene expression associated with co-infection, a significant association of the presence of HIV infection with the increase in CYP3A4 mRNA levels, and a trend observed for the downregulation of ABCB1 in patients using lamivudine." (PMID 37512019, 2023).
cocaine dependence (2 papers, 2013 to 2015). A psychologically and socially impaired state, with or without physiological changes, that develops as a result of using cocaine and which leads to compulsive behaviors to acquire the substance. "This was consistent with post hoc analyses in our sample, where we found that variation in ABCB1 was associated with DSM-IV alcohol and cocaine dependence criteria." (PMID 25918995, 2015). "ABCB1 has been implicated in substance use, and in post hoc tests we found that variation in ABCB1 was associated with DSM-IV alcohol and cocaine dependence criterion counts." (PMID 25918995, 2015). "Our findings provide preliminary evidence of the association between the ABCB1 polymorphism and heroin or cocaine dependence and the association between SLC6A3 and heroin or cocaine dependence was confirmed." (PMID 24892317, 2013).
colorectal tumour (2 papers, 2017 to 2022). "Four out of five examined colorectal tumours expressed ABCB1, however only few positive cancer cells were detected." (PMID 28877221, 2017).
congenital heart defects (2 papers, 2018 to 2024). "A variant in the ABCB1 gene that is associated with congenital heart disease in humans." (PMID 39062651, 2024).
cystic fibrosis (2 papers, 2013 to 2015). Autosomal recessive disorder caused by pathogenic variants in the CFTR gene (cystic fibrosis transmembrane conductance regulator), which encodes a chloride and bicarbonate channel expressed in epithelial cells, and follow the diagnosis criteria. "ABC (ATP-binding cassette) transporters are clinically important because drug pumps like P-glycoprotein (P-gp, ABCB1) confer multidrug resistance and mutant ABC proteins are responsible for many protein-folding diseases such as cystic fibrosis." (PMID 26507655, 2015).
delirium (2 papers, 2021 to 2025). A disorder characterized by confusion; inattentiveness; disorientation; illusions; hallucinations; agitation; and in some instances autonomic nervous system overactivity. "However, three of the 6 patients with MDR-1/ABCB1 or CYP3A4 gene mutation who received the first dose of ivermectin had mild (agitation) and two had severe side effects (agitation, delirium-like behavior, aggressive behavior and consciousness changes)." (PMID 33947344, 2021).
dependence (2 papers, 2020 to 2025). "Thus, it has been proposed that about 20% of the variance in the vulnerability to drug dependence might be due to common single nucleotide polymorphisms and, for instance, whether human ABCB1 influences cannabis-related phenotypes is under debate." (PMID 40005228, 2025). "Therefore, it may be conceivable that ABCB1 genetic polymorphisms may interact with mechanisms related to substance dependence, including nicotine addiction." (PMID 33329709, 2020).
dermatitis (2 papers, 2022 to 2023). An inflammatory process affecting the skin. "Additionally, the ABCB1 rs2032582 G > T/A polymorphism (A/T and G/T genotypes) was associated with any grade ≥ 2 skin disorders and grade ≥ 2 lymphocyte count decrease (Online Resource, Table F2, p = 0.017; Table F3, p = 0.033; respectively, in an additive model)." (PMID 36637703, 2023).
Encephalopathy (2 papers, 2012 to 2020). Encephalopathy is a term that means brain disease, damage, or malfunction. "For example, a recent case report detailed development of reversible encephalopathy and coma after a paediatric patient received a single dose of ivermectin, attributable to compound heterozygosity from two nonsense mutations in ABCB1, which encodes P-glycoprotein." (PMID 33198260, 2020).
endometrial cancer (2 papers, 2023 to 2024). Primary or metastatic malignant neoplasm involving the endometrium (mucous membrane that lines the endometrial cavity). "We performed a comprehensive analysis of mutations present in ABCB1, ABCC1, and ABCG2 transporters for endometrial cancer." (PMID 38766631, 2024).
fungal infections (2 papers, 2020 to 2025). "This study aimed to investigate the impact of the ABCB1-rs1045642 gene polymorphism on the blood drug concentrations of voriconazole in patients with severe invasive fungal infections." (PMID 40223939, 2025). "In this study, we investigated the association of SNPs in CYP2C19, CYP3A4, ABCB1, and FMO3 and the plasma concentrations of voriconazole in Thai patients with invasive fungal infections." (PMID 33124772, 2020).
gestational diabetes (2 papers, 2012 to 2017). Carbohydrate intolerance first diagnosed during pregnancy. "Pathophysiological changes in placental Abcb1 expression were also found to significantly alter maternal-fetal transfer of LPV in rat models of infection and gestational diabetes." (PMID 29064386, 2017).
invasive ductal breast carcinoma (2 papers, 2010 to 2016). The most common type of invasive breast carcinoma, accounting for approximately 70% of breast carcinomas. "In a previous study, ABCB1 promoter methylation has been detected in 39.3% of 28 small invasive ductal carcinomas." (PMID 27689338, 2016).
lymphopenia (2 papers, 2017 to 2022). Reduction in the number of lymphocytes. "ABCB1 rs2032582 was significantly associated with lymphopenia risk (OR = 2.23, 95%CI = 1.07–4.67, P = 0.033; multivariable analysis)." (PMID 28727815, 2017).
mesothelioma (2 papers, 2023 to 2025). A usually malignant and aggressive neoplasm of the mesothelium which is often associated with exposure to asbestos. "Similarly, dactolisib reversed drug resistance mediated by ABCB1 and ABCG2 in AML and mesothelioma cell lines, respectively." (PMID 37048130, 2023).
multiple system atrophy (2 papers, 2017 to 2024). Multiple system atrophy (MSA) is a neurodegenerative disorder characterized by autonomic failure (cardiovascular and/or urinary), parkinsonism, cerebellar impairment and corticospinal signs with a median survival of 6-9 years. "Using PET (11C-Verapamil tracer), Bartels and colleagues demonstrated the decreased BBB function of ABCB1 in disease-specific brain regions at later disease stages of PD, as well as multiple system atrophy (MSA) and Lewy body dementia (LBD)." (PMID 38727275, 2024).
Nephropathy (2 papers, 2008 to 2016). A nonspecific term referring to disease or damage of the kidneys. "Variants of the ABCB1 gene were associated with renal function in both Africans and Caucasians and may therefore confer susceptibility to nephropathy in humans." (PMID 18518969, 2008). "The ABCB1 gene therefore represents a new candidate gene for nephropathy in humans." (PMID 18518969, 2008).
neuritis (2 papers, 2019 to 2021). A neuropathy arising from inflammation of one or more nerves. "Likewise, our study also suggested that ABCB1 3435 TT/TC genotype were more likely to have neuritis (TT 88.2%, TC 22.2%, CC 21.6% P = 0.004) in taxane treatment." (PMID 31571407, 2019). "To further analyze the association between neuritis and ABCB1 polymorphisms, we subdivided toxicities into none (CTCAE grade 0), mild (CTCAE grade 1–2) and severe (CTCAE grade 3–4)." (PMID 31571407, 2019).
neurotoxicity (2 papers, 2023 to 2024). Toxicity that causes injury to the central or peripheral nervous system or damages its function. "Neurotoxicity was significantly associated with ABCB1 (rs9282564; TC vs. TT; OR: 4.25 [1.47–12.29], p = 0.007)." (PMID 38044950, 2023).
nicotine addiction (2 papers, 2020 to 2022). "Therefore, we aimed to investigate the effects of genetic polymorphisms of ABCB1 on the severity of nicotine dependence and clinical outcomes of smoking cessation therapies in a cohort of Turkish population." (PMID 33329709, 2020). "It is conceivable that ABCB1 genetic variants may play a role in nicotine addiction and may be affecting the status of tobacco consumption or outcomes of cessation therapies." (PMID 33329709, 2020). "In that study, we reported that genetic variants of the drug transporter ABCB1 and a particular haplotype (1236TT-2677TT-3435TT) were significantly associated with non-smoking status, while no other associations with genetic variants of ABCB1 or CYP2A6, CYP2B6 with nicotine addiction was found." (PMID 35222535, 2022).
Opioid Dependence (2 papers, 2013 to 2015). "Association of the ABCB1 rs2032582 - rs1045642 genotype patterns with opioid dependence (patients: n = 142, controls: n = 142)." (PMID 24086514, 2013).
osteoarthritis (2 papers, 2020 to 2022). A noninflammatory degenerative joint disease occurring chiefly in older persons, characterized by degeneration of the articular cartilage, hypertrophy of bone at the margins and changes in the synovial membrane. "In addition to changes in UGT1A1, polymorphisms in the transporter proteins SLCO1B1 and ABCB1 have been reported to influence the response of osteoarthritis patients to raloxifene treatment." (PMID 35453603, 2022).
ovarian adenocarcinoma (2 papers, 2007 to 2022). An adenocarcinoma that arises from the ovary. "Indeed, we have previously shown that ABCB1 expression remains unchanged after TSA treatment of the multidrug-resistant human ovarian adenocarcinoma cell line OV1/VCR, in which ABCB1 promoter is slightly hypermethylated compared to its sensitive IGROV1 counterpart." (PMID 17667922, 2007).